OSBPL9 (oxysterol binding protein like 9)
Description:
Interacts with OSBPL11 to function as lipid transfer proteins. Together they form a heterodimer that localizes at the ER-trans-Golgi membrane contact sites, and exchanges phosphatidylserine (1,2-diacyl-sn-glycero-3-phospho-L-serine, PS) for phosphatidylinositol-4-phosphate (1,2-diacyl-sn-glycero-3-phospho-(1D-myo-inositol 4-phosphate), PI(4)P) between the two organelles, a step that is critical for sphingomyelin synthesis in the Golgi complex. Interacts with OSBPL10 to function as lipid transfer proteins. Together they form a heterodimer that localizes at the ER-trans-Golgi membrane contact sites, and exchanges phosphatidylserine (1,2-diacyl-sn-glycero-3-phospho-L-serine, PS) for phosphatidylinositol-4-phosphate (1,2-diacyl-sn-glycero-3-phospho-(1D-myo-inositol 4-phosphate), PI(4)P) between the two organelles, a step that is critical for sphingomyelin synthesis in the Golgi complex.
Synonyms: ORP-9; ORP9
Tractability: PROTAC: ubiquitination databases record sites on it; its protein half-life has been measured.
Gene: Protein-coding gene on chromosome 1 (51,577,179 to 51,798,427, forward strand). Ensembl gene ENSG00000117859.
Subcellular location: Late endosome membrane; Golgi apparatus, trans-Golgi network membrane; Endoplasmic reticulum-Golgi intermediate compartment membrane
Subcellular location (Human Protein Atlas): Golgi apparatus; Vesicles
Pathways (Reactome):
Metabolism: Synthesis of bile acids and bile salts
Gene Ontology:
Molecular function: phosphatidylserine-phosphatidylinositol-4-phosphate exchange activity; protein binding; sterol transfer activity; lipid binding
Biological process: lysosomal membrane organization; phospholipid homeostasis; phospholipid transfer to membrane; bile acid biosynthetic process; intermembrane lipid transfer; sterol transport
Cellular component: endoplasmic reticulum-endosome membrane contact site; endoplasmic reticulum-trans-Golgi network membrane contact site; Golgi apparatus; lysosomal membrane; trans-Golgi network; cytosol; membrane; endoplasmic reticulum-Golgi intermediate compartment membrane; late endosome membrane
Genetic constraint (gnomAD): Loss-of-function variants: 23 observed, 78.43 expected, observed/expected ratio (o/e) 0.29, 90% interval 0.21 to 0.41. The upper end of that interval is the gene's LOEUF score, 0.41, which puts it in group 1 of 6, group 1 being the genes least tolerant of losing a copy. Missense variants: 489 observed, 759.1 expected, observed/expected ratio (o/e) 0.64, 90% interval 0.6 to 0.69. Synonymous variants: 218 observed, 262.06 expected, observed/expected ratio (o/e) 0.83, 90% interval 0.74 to 0.93.
Homologues: Orthologues: chimpanzee OSBPL9 (98% identical), macaque OSBPL9 (98% identical), pig OSBPL9 (97% identical), rat Osbpl9 (97% identical), guinea pig OSBPL9 (96% identical), rabbit OSBPL9 (96% identical), mouse Osbpl9 (96% identical), dog OSBPL9 (96% identical), tropical clawed frog osbpl9 (86% identical), zebrafish osbpl9 (83% identical), Drosophila melanogaster CG1513 (51% identical), Caenorhabditis elegans obr-4 (43% identical), and 1 more. Paralogues in human: OSBPL11 (38% identical), OSBPL10 (37% identical), OSBPL8 (22% identical), OSBPL5 (22% identical), OSBPL6 (20% identical), OSBPL3 (19% identical), OSBP2 (19% identical), OSBP (19% identical), OSBPL1A (18% identical), OSBPL7 (18% identical), OSBPL2 (13% identical).
Diseases named in the same sentence as OSBPL9 in open-access papers:
OSBPL9 is named in the same sentence as 15 diseases in open-access papers, as found by Europe PMC text mining. Sharing a sentence is not in itself a finding about the gene and the disease. The quoted sentences say what the papers report.
Intellectual disability (2 papers, 2025). "Denovo missense mutations in the OSBPL9 gene have been previously reported to be associated with intellectual disability." (PMID 40182349, 2025). "On the other hand, the SCAPER gene was linked to retinitis pigmentosa and intellectual disability and the OSBPL9 gene was identified as a gene involved in canine hypoadrenocorticism." (PMID 40003092, 2025).
neuroblastoma (2 papers, 2018 to 2025). Neuroblastoma (NB) is the most common solid, extracranial childhood tumor. "Among the public microarray data, we found that, in human neuroblastoma cells, SH-SY5Y (GEO accession: GSE24497) and IMR-32 (GSE6976), OSBPL9 expression is significantly upregulated upon thapsigargin treatment." (PMID 32161797, 2018).
arthrogryposis (1 paper, 2025). A rare, non-progressive congenital disorder characterized by multiple joint contractures which are present at birth. "Herein, we report for the first time, to the best of our knowledge, a novel homozygous nonsense variant in the OSBPL9 gene in a consanguineous family with two fetuses with cerebral ventriculomegaly, cerebellar hypoplasia, and arthrogryposis multiplex." (PMID 40182349, 2025). "We thus identified a novel homozygous nonsense variant in the OSBPL9 gene in a family with two fetuses with cerebral ventriculomegaly, cerebellar hypoplasia, and arthrogryposis multiplex inherited in a recessive manner." (PMID 40182349, 2025).
lipid metabolism disorders (1 paper, 2025). "In this study, seven core genes (Amacr, Cyp39a1, Echs1, Gpd2, Osbpl9, Acsl4, and Mcee) closely associated with lipid metabolism disorders in AP were systematically identified through the integration of bioinformatics and machine learning approaches." (PMID 41007695, 2025).
steatosis (1 paper, 2018). Increased lipid within the cytoplasm of cells. "More specifically, perturbation in endoplasmic reticulum and vesicles through the genes MUL1, TMEM135, OSBPL9, SCD1, SREBP-1C, GPAT3 can lead to steatosis." (PMID 30279702, 2018).
tumor (5 papers, 2020 to 2025). "Osbpl9 has been relatively understudied and previously linked primarily to the tumor microenvironment." (PMID 41007695, 2025). "Six upregulated and mutated tumor antigens related to NMD, and infiltration of APCs were identified in patients with BLCA, including HP1BP3, OSBPL9, SSH3, ZCCHC8, FANCI, and EIF4A2." (PMID 36761744, 2023). "In the subnetwork related to tumor progression, the hubs from the blue module are the most connected, such as the genes Cmas, Kmt2a, Golt1b, Cdc34, Manf, Sco1, and Thoc3, followed by hubs from the light cyan (Extl2, Commd3, Wdr41, Keap1, Osbpl9) and pink modules." (PMID 32831131, 2020). "The results demonstrated that the protein expressions of OSBPL2 and OSBPL3 were elevated while OSBPL5, OSBPL6, OSBPL9, OSBPL10, and OSBPL11 were lowly expressed in tumor samples." (PMID 36918840, 2023). "As to the protein expression, OSBPL2 and OSBPL3 were significantly elevated and OSBPL5, OSBPL6, OSBPL9, OSBPL10, OSBPL11 were downregulated in tumor samples." (PMID 36918840, 2023). "In OvCa_84 tumor sample, the predicted RE neoantigen ILVRSLLVL from Oxysterol Binding Protein Like 9 (OSBPL9) (chr1:51752522) was experimentally discovered in complexed with MHC I via mass spectrometry with high confidence (q value <0.05)." (PMID 33363023, 2020). "Six tumor antigens (HP1BP3, OSBPL9, SSH3, ZCCHC8, FANCI and EIF4A2) were correlated with the expression of NMD factors and infiltration of APCs, which may be promising candidates for mRNA vaccines." (PMID 36761744, 2023).
OSBPL9 also shares sentences with these, for which no sentence is quoted: asthenozoospermia (1 paper); atherosclerosis (1); Cerebellar hypoplasia (1); colorectal cancer (1); infection (1); neurological disorders (1); pancreatic cancer (1); retinitis pigmentosa (1); Ventriculomegaly (1).